SNORA73B (small nucleolar RNA, H/ACA box 73B)
Synonyms: U17B; E1c; 105A; RNU105A; RNU17B
Gene: Small nucleolar RNA gene on chromosome 1 (28,508,559 to 28,508,762, forward strand). Ensembl gene ENSG00000200087.
Gene Ontology:
Biological process: RNA processing
Cellular component: nucleolus
Homologues: Orthologues: chimpanzee SNORA73 (100% identical), macaque SNORA73 (98% identical), dog SNORA73 (91% identical), guinea pig SNORA73 (88% identical). Paralogues in human: SNORA73A (94% identical), RNU105B (85% identical), RNU105C (85% identical), SNORA73 (85% identical), SNORA73 (84% identical), SNORA73 (78% identical), SNORA73 (41% identical).
Diseases named in the same sentence as SNORA73B in open-access papers:
SNORA73B is named in the same sentence as 5 diseases in open-access papers, as found by Europe PMC text mining. Sharing a sentence is not in itself a finding about the gene and the disease. The quoted sentences say what the papers report.
colorectal cancer (1 paper, 2025). A primary or metastatic malignant neoplasm that affects the colon or rectum. "The Rn7sk, Rpph1, Rn7sl1, Rn7sl2, Znf460, Snord17, Snora73b, H1-4, H4c12, and H3c7 genes were discovered to be highly upregulated in the tumor tissue collected from colorectal cancer patients." (PMID 40427657, 2025).
SNORA73B also shares sentences with these, for which no sentence is quoted: cancer (3 papers); endometrial cancer (2); tumor (2); leukemia (1).